TNFRSF10A (TNF receptor superfamily member 10a)
Description:
Receptor for the cytotoxic ligand TNFSF10/TRAIL. The adapter molecule FADD recruits caspase-8 to the activated receptor. The resulting death-inducing signaling complex (DISC) performs caspase-8 proteolytic activation which initiates the subsequent cascade of caspases (aspartate-specific cysteine proteases) mediating apoptosis. Promotes the activation of NF-kappa-B.
Synonyms: CD261; APO2; DR4; TRAILR1; TRAILR-1
Tractability: Antibody: a drug acting on it is in phase 2 or 3 trials; UniProt places it where antibodies can reach, with high confidence; its Gene Ontology location is reachable by antibodies, with high confidence; UniProt predicts a signal peptide or a membrane-spanning region. PROTAC: ubiquitination databases record sites on it; a small molecule that binds it is known. Other modalities: a drug acting on it is in phase 2 or 3 trials.
Target class: Membrane receptor
Gene: Protein-coding gene on chromosome 8 (23,190,452 to 23,225,121, reverse strand). Ensembl gene ENSG00000104689.
Subcellular location: Cell membrane; Membrane raft; Cytoplasm, cytosol
Pathways (Reactome):
Programmed Cell Death: CASP8 activity is inhibited; Caspase activation via Death Receptors in the presence of ligand; Dimerization of procaspase-8; RIPK1-mediated regulated necrosis; Regulation by c-FLIP
Hemostasis: Cell surface interactions at the vascular wall
Signal Transduction: TRAIL signaling
Gene Ontology:
Molecular function: identical protein binding; protease binding; protein binding; death receptor activity; signaling receptor activity; TRAIL binding
Biological process: cellular response to mechanical stimulus; extrinsic apoptotic signaling pathway; TRAIL-activated apoptotic signaling pathway; activation of NF-kappaB-inducing kinase activity; apoptotic process; extrinsic apoptotic signaling pathway via death domain receptors; positive regulation of apoptotic process; signal transduction
Cellular component: cell surface; cytosol; Golgi apparatus; membrane raft; plasma membrane; plasma membrane raft
Genetic constraint (gnomAD): Loss-of-function variants: 40 observed, 40.29 expected, observed/expected ratio (o/e) 0.99, 90% interval 0.77 to 1.29. The upper end of that interval is the gene's LOEUF score, 1.29, which puts it in group 5 of 6, group 1 being the genes least tolerant of losing a copy. Missense variants: 671 observed, 580.32 expected, observed/expected ratio (o/e) 1.16, 90% interval 1.09 to 1.23. Synonymous variants: 258 observed, 227.33 expected, observed/expected ratio (o/e) 1.13, 90% interval 1.02 to 1.26.
Homologues: Orthologues: chimpanzee TNFRSF10A (97% identical), macaque TNFRSF10A (85% identical), zebrafish nradd (12% identical), tropical clawed frog nradd (10% identical), zebrafish tnfrsf1b (10% identical), zebrafish tnfrsf11a (10% identical), zebrafish tnfrsfa (10% identical), zebrafish hdr (9% identical), zebrafish cd40 (8% identical). Paralogues in human: TNFRSF10B (49% identical), TNFRSF10D (39% identical), TNFRSF10C (20% identical), TNFRSF1A (14% identical), TNFRSF21 (13% identical), TNFRSF25 (12% identical), LTBR (12% identical), TNFRSF11A (12% identical), NGFR (11% identical), TNFRSF1B (11% identical), FAS (10% identical), TNFRSF8 (10% identical), and 9 more.